IL19 (interleukin 19)
Diseases named in the same sentence as IL19 in open-access papers (continued):
Sharing a sentence is not in itself a finding about the gene and the disease.
IL19 also shares sentences with these, for which no sentence is quoted: brain infarct (2 papers); immune diseases (2); myocardial infarction (2); Alzheimer’s disease (1); amyotrophic lateral sclerosis (1); aristolochic acid nephropathy (1); blood cancers (1); cardiovascular disease (1); cerebral infarction (1); Cerebral ischemia (1); chronic obstructive pulmonary disease (1); conjunctivitis (1); cyst (1); Down syndrome (1); dry eye (1); dysplasia (1); fibrosarcoma (1); gastric cancer (1); gastrointestinal disease (1); gastrointestinal infections (1); glioma (1); hearing loss (1); HELLP syndrome (1); hydronephrosis (1); hyperthyroidism (1); intestinal inflammation (1); iron deficient anemia (1); Lipedema (1); malaria (1); metastatic tumors (1).
A further 11 diseases each share a sentence with IL19 in 1 paper.